TNF (tumor necrosis factor)
Diseases named in the same sentence as TNF in open-access papers (continued):
Sharing a sentence is not in itself a finding about the gene and the disease.
cancer (continued). "Inflammatory cytokines like IL‐6 and TNF‐α released by cancer cells activate adipocytes in the TME, shifting them from storage to lipolysis mode and releasing free fatty acids for cancer cells to utilize." (PMID 40391753, 2025). "For example, the cytokine tumor necrosis factor-alpha (TNF-α), produced during inflammation, can activate NF-κB and other pro-survival pathways in cancer cells." (PMID 39856066, 2025). "In the present study, we found that TNF, IFN, IRF1 and IRF5, IL-6, IL-1β, and CCL3 were upregulated in EBV-positive SCC25 cancer cells compared to EBV-negative SCC25 cancer cells." (PMID 39941858, 2025). "There are many cytokines and chemokines that can facilitate cell fusion; however, the most relevant to cancer are platelet-derived growth factor (PDGF), tumor necrosis factor alpha (TNF-α), epidermal growth factor (EGF), and interleukin-4 (IL-4)." (PMID 40723152, 2025). "Critical targets such as TNF, EGFR, ESR1, HIF1A, HSP90AA1, and SRC were involved in pathways including chemical carcinogenesis, PI3K‐Akt signaling, proteoglycans in cancer, receptor activation in chemical carcinogenesis, and immunomodulation." (PMID 40144560, 2025). "Molecular docking revealed strong binding affinities between these compounds and cancer-related targets (AKT1, CDK2, ERK1, TNFα), with simplicildone D and mollicellin G demonstrating particularly high interactions." (PMID 40942174, 2025). "Recently, a study showed that TNF-α and IFN-γ enhance the cancer cells invasiveness by downregulating the expression of E-cadherin." (PMID 40821783, 2025). "TNFα is an important TME signal to promote cancer cell death and neoantigen presentation, overall promoting immune response in cancer." (PMID 41108578, 2025). "Assessing the temporal secretion of 34 cytokines (including TNF-alpha) and 15 immune checkpoint proteins (including TNFRSF9 and TNFSF9), we generate the most comprehensive ZIKV-infected cancer cell secretome to date." (PMID 40240536, 2025). "Elevated levels of TNF-α, IL-6, IFN-γ, and IL-12p70 confirmed strong immune activation, highlighting its potential as a cancer treatment platform." (PMID 41228373, 2025). "Enhanced T cell activity promotes cancer cell death through effector mechanisms involving perforin (PFN), granzyme B (GzmB), interferon-gamma (IFNγ), and tumor necrosis factor-alpha (TNFα)." (PMID 40806510, 2025). "Four cancer-related hub genes (CRGs) were identified: Interferon Regulatory Factor 7 (IRF7), Formin Homology 2 Domain Containing 1 (FHOD1), Tumor Necrosis Factor (TNF), and Zinc Finger SWIM Domain Containing 3 (ZSWIM3)." (PMID 41262249, 2025). "We have shown that the mechanism involved appears to be through cytokines such as EGF, PDGF, TNF-α, IFN-γ or IL-6, which activate signaling pathways within the cancer cells themselves that lead to FN1 production." (PMID 40096084, 2025). "NK cell–produced TNFα and IFNγ induce ICAM-1 upregulation on K562 cancer cells, which then enhances the cytotoxicity of cancer cells by promoting their conjugate formation with NK cells." (PMID 41128663, 2025). "All three lymphocyte cell types showed enrichment in pathways strongly involved in immune cell response to cancer, like PD-L1/PD-1 checkpoint, ErbB, MAPK, TNF, PI3K/Akt/mTOR, EGFR, VEGF, NF-kappa B signaling." (PMID 40954493, 2025). "In particular, we examine the role of circRNAs in TGF‐β, IL‐6, IL‐10, TNF‐α, VEGF, FGF, PDGF, and chemokine signaling in cancer." (PMID 40356340, 2025). "Numerous studies have identified positive correlations between serum inflammatory biomarkers and cancer-related mortality, including CRP, IL-6, leukocytes, neutrophils, haptoglobin, albumin, and TNF." (PMID 40563468, 2025).
cancer (continued). "Other cytokines, with a dual role in cancer progression, were also found at higher levels in the ASC-derived secretome compared to OC-CM, including TNF-α and TRAIL." (PMID 40072102, 2025). "C3 is dominated by infiltration of neutrophils and pro-inflammatory cytokines (such as IL-6, TNF-α) and is commonly found in tumors with HPV-related cancers or a background of chronic inflammation." (PMID 41474538, 2025). "First, it induces the production of proinflammatory cytokines such as TNF-α, IL-6, and IL-1β, as well as chemokines such as CXCL1 and CCL2, which recruit immune cells, stimulate angiogenesis, and enhance cancer cell proliferation." (PMID 40562870, 2025). "Inflammatory cytokines associated with cancer, including interleukin-6 (IL-6), interleukin-1, and tumor necrosis factor-alpha (TNF-α), suppress albumin synthesis and contribute to the development of cancer cachexia." (PMID 40786260, 2025). "In summary, SsnB exerts its anti-cancer effects by downregulating MyD88, p-ERK, and p-NFκB signaling, along with suppressing the pro-inflammatory cytokines TNF-α, IL-1β, and IL-6." (PMID 40143078, 2025). "Exercise has been shown to regulate inflammatory factors such as interleukin-6 (IL-6) and tumor necrosis factor-alpha (TNF-α), reducing cancer-related side effects and helping restore muscle mass homeostasis." (PMID 40104495, 2025). "In cancer cachexia, components of the UPS are activated by the inflammatory cytokines TNF-α and IL-6 via the NF-κB and STAT3 pathways, which upregulate MuRF1 and atrogin-1 expression." (PMID 40869331, 2025). "In patients with advanced cancer, elevated CRP levels are commonly experienced in conjunction with elevated levels of IL-1β and TNF." (PMID 40420174, 2025). "The cancer cells were preincubated with NAC and subsequently treated with NP4 showed a reduced number of TNF-α secreted from the macrophages, suggesting that macrophage activation is associated with the NP4-induced oxidative stress." (PMID 39477929, 2024). "The literature reveals that TNF-α, VEGF-α, COX-2, MMP-2, Caspase-3, and NOS are interconnected in various cancer processes." (PMID 38918540, 2024). "Many natural compounds were also found to target TNF-α/NF-κB and DR5 expression/pathway in cancer cells." (PMID 38698424, 2024). "Studies have shown increased concentrations of multiple cytokines, including interleukin 6, TNFα, interleukin 8, the cytokines MIF, TGFβ, interleukin 10 and interleukin 18 in patients with cancer." (PMID 39020272, 2024). "As demonstrated by Carswell, elevated levels of TNFα can eliminate MCA-induced sarcomas, and approximately 28% of cancers are sensitive to sTNFα." (PMID 38461238, 2024). "In the cancer cells, overexpression of NF-κB is observed which suppresses programmed cell death by exciting expression of IAP, cFLIP, and TNF – inhibitory genes." (PMID 38700244, 2024). "CREPT, in turn, regulates the transduction of downstream signals of TNF by modulating the expression of TNFR2 and PI3K, thereby promoting inflammation-to-cancer transition." (PMID 38169511, 2024). "Also, studies found that cancer cell-derived exosomal miRNAs can bind to TLRs in macrophages and intestinal cells and stimulate NF-κB pathway with subsequent release of the pro-inflammatory and pro-metastatic cytokines IL-6 and TNF-α which stimulate tumor growth and metastasis." (PMID 38987740, 2024). "Exosomal ligands programmed death ligand-1 (PD-L1), TNF, FasL, and TRAIL are interesting potential targets for cancer therapies since their receptors are present on the cancer cell surface." (PMID 39267734, 2024).
cancer (continued). "Our data showed that RO extracts significantly decreased the quantities of TNFα, VEGFa, COX-2, and MMP2 in A549 cancer cells in combination with 5-FU." (PMID 38918540, 2024). "Several signalling pathways are involved in the pathogenesis of RSA, such as the TNF-α signalling pathway, HIF-1 signalling pathway, oestrogen signalling pathway, proteoglycans in cancer cells, and FoxO signalling pathway." (PMID 38872917, 2024). "The results showed that the pathways mainly included insulin resistance, cancer pathway, PI3K-Akt signaling pathway, FOXO signaling pathway, TNF signaling pathway, and VEGF signaling pathway." (PMID 38921004, 2024). "Another study indicated that after treatment with the nanoformulated LPO and LF on chitosan NPs, there was a considerable suppressed various pro-inflammatory markers, including TNF-α, IL-6, VEGF, and NF-κB in the treated breast MCF-7 and MDA cancer cells." (PMID 39438495, 2024). "It inhibits tumor necrosis factor (TNF), frequently deregulated in cancers, and impedes NF-κB activation, a protein complex crucial for DNA transcription, cytokine production, and cell survival, by inhibiting IκB kinase (IKK)." (PMID 39001443, 2024). "The silencing of interferon regulatory factor 6 (Irf6) in cancer cells by EMT-transcription factors (EMT-TFs) ZEB1 and SNAIL minimize the pro-apoptotic effects of tumor necrosis factor (TNF) α." (PMID 38817612, 2024). "Measurement of systemic biomarker concentrations revealed statistically significant increases (p < 0.05) in all of the following biomarkers in the group of cancer patients relative to controls: blood platelets, NLR, PLR, SII, CRP, IL-6, IL-8, and TNFα." (PMID 38744744, 2024). "Accordingly, the inhibition of inflammation promoting cancer is anticipated by targeting key mediators and/or regulatory factors (such as NF‐κB and STAT3) of inflammatory pathways and cytokines (e.g., IL‐1, TNF, and IL‐6)." (PMID 38766879, 2024). "These cytokines are part of the broader inflammatory response that includes other key players like tumor necrosis factor-alpha (TNF-α) and transforming growth factor-beta (TGF-β), which collectively contribute to cancer initiation, progression, and metastasis." (PMID 39125732, 2024). "NF-κB signaling via expression regulation of multiple target genes (e.g., BCLXL, BCL2, BCLXS, TNF-α, IL6, XIAP, and VEGF) represents an essential cellular pathway that is extensively involved in acquired therapy resistance in cancer." (PMID 37789138, 2024). "TNF-α can also activate the expression of T-cell immunoglobulin mucin-3 (TIM-3), allowing cancer cell-expressed Galectin-3 (Gal-3) to block T cells by binding to TIM-3 on the T cell membrane." (PMID 39101140, 2024). "Cytotoxic effector CD8+ T cells can directly recognize and kill cancer cells by releasing cytotoxic molecules, such as granzymes and perforin, as well as pro-inflammatory cytokines like IFN-γ and TNF-α." (PMID 38444857, 2024). "In common with TRIB3, a potential link between TRIB2 and HIF-1α has been reported, as depletion of TRIB2 significantly decreased the effect of TNF-α on HIF-1α stability and accumulation in multiple cancer cell lines." (PMID 38896446, 2024). "On the other hand, astrocytes induce BCCs to produce high amounts of IL-1β and TNF-α, which activate NOTCH signaling, promoting the stemness of cancer stem cells and ultimately tumor growth." (PMID 39766062, 2024). "Adhesion studies in vitro with brain ECs demonstrated that TNFα inflammatory signaling increased the expression of selected adhesion proteins in ECs (ICAM1, CD112, CD47, JAM-C) and in cancer cells (ALCAM, CD6)." (PMID 38473273, 2024). "Intermittent hypoxia (IH) in OSA promotes cancer progression by upregulating HIF-1α and transforming growth factor β1 (TGF-β1), which alter cytokine levels, increase TNF-α and IL-10, and decrease IL-17, suppressing antitumor immunity." (PMID 39070143, 2024).
cancer (continued). "This review explores the mechanisms of TNF-α-induced COX-2/PGE2 expression, a significant pathophysiological feature of cancer development." (PMID 39830670, 2024). "The differentiation of naïve CD8+ T cells into effective CD8+ T cells enables these cells to combat infections and cancers through the release of IFN-γ, TNF-α, and cytotoxic molecules." (PMID 38566199, 2024). "Meanwhile, the IGF-I also enhanced the tumor necrosis factor α (TNF-α) and interleukin (IL)-8 cytokine expression in anti-cancer response." (PMID 38329437, 2024). "Studies evaluating the expression of classic pro-inflammatory cytokines (TNF-α, IL-1β, IL-6, IL-17, IL-18, IL-33) in the spinal cord, PAG, and DRG revealed upregulation following inoculation of cancer cells to establish the BCP models." (PMID 38940936, 2024). "Despite all the therapeutic impediments of TNF-α/TRAIL application, the cytotoxic cytokines remain the strongest natural defense to cancer in humans." (PMID 38698424, 2024). "The principal participants in the battle against cancer cells are the CTLs that produce IFN-γ, TNF, perforin, and granzymes." (PMID 38835055, 2024). "Although associations have been identified between IL-4, IL-6, IL-8, IL-10, IL-1β, TNF-α, COMT, CLOCK, PER, and 5-HTTLPR-related genes and cancer-related fatigue, the relationship between IL-6 and cancer-related fatigue remains controversial." (PMID 39372868, 2024). "Tumor necrosis factor-α (TNF-α) is a pivotal inflammatory mediator in TME and is on the radar of many anti-inflammatory as well as anti-cancer treatments." (PMID 39416904, 2024). "Although GB cells typically do not express IDO, it is activated when GB cells are identified by TILs or NK cells and exposed to important anti-cancer cytokines such as IFN-γ and TNF-α." (PMID 38473776, 2024). "TAMs produce cytokines that induce epithelial-mesenchymal transition (EMT) and cancer stem cell (CSC) characteristics in HCC cells, thus supporting invasiveness and metastasis through the secretion of TGF-β1 and TNF-α." (PMID 39796695, 2024). "Pathways involving growth factors (e.g., TGF-β, VEGF, and EGF), cytokines (e.g., IL-6 and TNF-α), and chemokines (e.g., CXCL12) play critical roles in modulating the behavior of both cancer and stromal cells." (PMID 39600368, 2024). "In a previous study, Ruminococcus was found to induce dendritic cells to produce tumour necrosis factor alpha (TNF-α) by making a complex glucan, while TNF-α was found to promote cancer." (PMID 39553581, 2024). "Patients with ESRD have high levels of proinflammatory cytokines, including interleukin (IL)-6, IL-12, tumor necrosis factor (TNF)-α, and interferon (IFN)-γ, which stimulate cancer antigen presentation." (PMID 39335107, 2024). "Tumor necrosis factor α (TNF-α) is a protumor factor in a chronic inflammatory environment, including tumors and many cancers." (PMID 38654309, 2024). "If microglia are activated, they begin to produce proinflammatory factors such as TNFα, IL-1β, IL-6, VEGF, and these can increase EC permeability and create an opportunity for the entry of circulating cancer cells." (PMID 38473273, 2024). "SDC4high CSCs exhibited high expression of genes such as KLF6, ATF3, and CXCL2, with Kyoto Encyclopedia of Genes and Genomes (KEGG) enrichment analysis revealing their involvement in TNF signaling, MAPK signaling, apoptosis, and cancer development." (PMID 39107908, 2024). "Another study reported the design of an electrophoretic flower-like MoS2 and TNF-α coated ITO electrode, which achieved the lowest LOD detection (0.202 pg ml−1) in cancer patient blood samples." (PMID 38920613, 2024). "Chronic inflammation upregulates several proinflammatory cytokines, mainly IL-1, TNF-α, IFN-γ, IL-6, IL-12, IL-23, and IL-17, involved in both the initiation and progression of cancer." (PMID 38256080, 2024).
cancer (continued). "Cancer cells expressing cGAS poses the ability to recognize cytoplasmic DNA and generate cGAMP, which in turn stimulates the secretion of IFN-β and tumor necrosis factor alpha (TNF-α) through the STING pathway." (PMID 38817608, 2024). "Anti-tumor necrosis factor (TNF) α agents are not recommended in these patients, not only because of their potent immunosuppressive effects and risk of cancer progression, but also due to a lack of efficacy that may be explained by a different pathogenic mechanism, not directly dependent on TNF α." (PMID 38541099, 2024). "Acting on CD8+T cells by upregulating the levels of TNFα, IL-2, and IL-12, RSV enhanced their cytotoxic effect, an important step in halting the growth of cancer." (PMID 39220125, 2024). "It inhibits inflammatory cytokines such as TNF-α, IL-6, and IL-1β, improves cognitive functions by regulating the NGF-BDNF-CREB signaling pathway, and shows antiproliferative effects on cancer cell lines like AGS, HT-1080, and HT-29." (PMID 39124930, 2024). "WAT releases inflammatory molecules, such as IL6, TNF, and CCL2, which can contribute to cancer progression by promoting inflammation." (PMID 39011399, 2024). "Key targets such as TNF, PTGS2, PRKACA, HSP90AB1, RELA, and NFKBIA appeared to be involved in chemical carcinogenesis–receptor activation, pathways in cancer, IL-17 signaling pathway, cholinergic synapse pathway, and regulation of lipolysis in adipocytes." (PMID 39064924, 2024). "Of significance, the DEmRNAs consistently upregulated in both the SR cells and SR+Rego cells exhibited significant enrichment in pathways encompassing cancer, PI3K-Akt signaling, focal adhesion, relaxin signaling, and TNF signaling pathways." (PMID 38603701, 2024). "According to KEGG enrichment analysis, the primary signaling pathways involved include the cancer pathway, MAPK signaling pathway, AGE–RAGE signaling, EGFR, TNF, HIF-1, and the PD-L1/PD-1 checkpoint pathways." (PMID 39612458, 2024). "Both TNF-α and IL-6 signaling have been shown to play protumorigenic and prometastatic roles in BRCA, particularly with secretion from/to cancer cells." (PMID 39642223, 2024). "From the perspective of cancer cells, HAT down-regulated the expression of TGF-β, TNF-α, EGF, CCL2, CXCL1, and CXCL12, crucial angiogenic and chemotactic factors for ECs." (PMID 38338342, 2024). "Dex-treatment leads to the destabilization of ARE-containing mRNAs of TNF and CXCL8, and PTGS2 in cancer cells." (PMID 38195703, 2024). "Anethole has affected the TNF-α and JAK-STAT pathways of cancer development and showed cancer-preventive activity." (PMID 39246660, 2024). "While it was evidently inhibited under the treatment of BYL719, the treatment also influenced the other cancer-related pathways, such as JAK-STAT, NF-kB, Ras, TNF signaling pathways." (PMID 38253702, 2024). "As a mediator of TNF-α signaling, TRAF2 has been considered as a potential therapeutic target in cancers." (PMID 38698424, 2024). "This intricate interaction beckons further investigation to decode the pathways through which IL-1 and TNF affect BCAR3 gene activity, particularly focusing on its implications in cancer biology." (PMID 38730626, 2024). "There is a potential role for the use of biomarkers in the diagnosis of cancer cachexia—human CC patients have been demonstrated to have elevated C-reactive protein (CRP), fibrinogen, IL1, IL6 and TNF-a." (PMID 38674936, 2024).